C10orf105 (chromosome 10 open reading frame 105)
Synonyms: FLJ00245
Tractability: Antibody: UniProt predicts a signal peptide or a membrane-spanning region.
Gene: Protein-coding gene on chromosome 10 (71,711,701 to 71,737,824, reverse strand). Ensembl gene ENSG00000214688.
Subcellular location: Membrane
Gene Ontology:
Cellular component: membrane
Genetic constraint (gnomAD): Loss-of-function variants: 4 observed, 1.11 expected, observed/expected ratio (o/e) 3.59. That is too few expected variants to judge how well the gene tolerates losing a copy. Missense variants: 209 observed, 172.57 expected, observed/expected ratio (o/e) 1.21, 90% interval 1.08 to 1.36. Synonymous variants: 95 observed, 72.67 expected, observed/expected ratio (o/e) 1.31, 90% interval 1.11 to 1.55.
Homologues: Orthologues: chimpanzee C10H10orf105 (99% identical), macaque C9H10orf105 (92% identical), dog C10orf105 (76% identical), guinea pig C10orf105 (72% identical), pig C10orf105 (72% identical), rat Gm17455 (65% identical), mouse Gm17455 (65% identical), rabbit C10orf105 (53% identical), tropical clawed frog C10orf105 (49% identical).